FOXE1 (forkhead box E1)
Diseases named in the same sentence as FOXE1 in open-access papers (continued):
Sharing a sentence is not in itself a finding about the gene and the disease.
colorectal cancer (4 papers, 2020 to 2024). A primary or metastatic malignant neoplasm that affects the colon or rectum. "In this study, we examined FOXE1 expression and methylation in normal colon mucosa, colorectal cancer (CRC) cell lines, and primary tumors by immunohistochemistry, semi-quantitative RT-PCR, methylation-specific PCR, and bisulfite genomic sequencing." (PMID 38734646, 2024). "Subsequently, we established colon cancer cell lines with stable FOXE1 expression to observe the biological effect on colorectal cancer, including cell growth, migration, actin cytoskeleton, and growth of human colorectal xenografts in nude mice." (PMID 38734646, 2024). "However, the expression and function of FOXE1 in the tumorigenesis of colorectal cancer remain still unknown." (PMID 38734646, 2024). "Low expression of FOXE1, a member of Forkhead box (FOX) transcription factor family that plays vital roles in cancers, contributes to poor prognosis of colorectal cancer (CRC) patients." (PMID 31918722, 2020). "FOXE1 methylation was frequently seen in association with a complete absence of or downregulated gene expression, and FOXE1 plays a suppressive role in the development and progression of colorectal cancer." (PMID 38734646, 2024). "However, until now the mechanism of action of FOXE1 in colorectal cancer is not clear." (PMID 38734646, 2024).
pancreatic cancer (4 papers, 2018 to 2024). "Hypermethylation of FOXE1 was observed in 75% of pancreatic carcinomas, as well as in squamous cell cancer and in salivary gland carcinoma." (PMID 39588344, 2024). "In a model of pancreatic cancer, Afadin regulates Snail expression by antagonizing the interaction between Dvl2 and FOXE1." (PMID 30473688, 2018).
anaplastic thyroid cancer (3 papers, 2016 to 2024). "Nevertheless, these allelic variants were associated with altered FOXE1 expression in PTC tissues, whereas complete loss of FOXE1 expression is often found in anaplastic thyroid cancer (ATC)." (PMID 27852061, 2016). "Specifically, absent FOXE1 expression is observed in most anaplastic thyroid cancers (ATCs)." (PMID 38396644, 2024).
cleft lip (3 papers, 2021 to 2024). Congenital defect in the upper lip where the maxillary prominence fails to merge with the merged medial nasal prominences. "It is thought that FOXE1 gene variants together with other genes involved in facial development interact with each other and jointly increase the susceptibility of craniofacial defect formation, including cleft lip and palate." (PMID 33917041, 2021). "This test revealed a statistically significant difference in the number of FOXE1 immunopositive connective tissue cells between the controls and the unilateral cleft lip tissue group (U=16.0, p=0.003)." (PMID 37733420, 2022). "In the unilateral cleft lip tissue group the median number of FOXE1 positive epitheliocytes was moderate (++) and it ranged from a few (+) to numerous (+++) number of FOXE1 positive surface epitheliocytes." (PMID 37733420, 2022). "The median number of FOXE1 positive connective tissue cells in the unilateral cleft lip tissue group was moderate (++) and it ranged from a few (+) positive cells to numerous to abundant (+++/++++) FOXE1 positive cells." (PMID 37733420, 2022). "Transcription factors BARX1, FOXE1 are probably involved with the formation of both unilateral cleft lip and bilateral cleft lip morphopathogenesis processes within the postnatal cleft affected tissue." (PMID 37733420, 2022). "In the bilateral cleft lip tissue group the median number of FOXE1 positive cells in the surface epithelium was moderate to numerous – numerous (++/+++ - +++) and it ranged from a few (+) to numerous (+++) number of immunopositive epitheliocytes." (PMID 37733420, 2022). "The aim of this study was to detect and compare the immunohistochemical expression of cleft candidate gene coded proteins (DLX4, MSX2, HOXB3, SHH, PAX7, SOX3, WNT3A, and FOXE1) in the non-syndromic unilateral cleft lip patient tissue and control group tissue." (PMID 33917041, 2021). "This could mean that the pathogenetic role of FOXE1 might be quite similar in both types of lip clefts." (PMID 37733420, 2022). "This could indicate a close interaction between three factors – FOXE1, HOXB3, and MSX2 within bilateral cleft lip tissue." (PMID 37733420, 2022). "FOXE1 and BARX1 could be involved with both unilateral and bilateral cleft lip morphopathogenesis." (PMID 37733420, 2022).
multinodular goiter (3 papers, 2017 to 2024). Nodular goiter characterized by more than one discrete tissue mass. "Yet the same group showed that FOXE1 overexpression in mouse thyroids developed multinodular goiter but not cancer." (PMID 39588344, 2024).
athyreosis (2 papers, 2017 to 2023). Athyreosis is a form of thyroid dysgenesis characterized by complete absence of thyroid tissue that results in primary congenital hypothyroidism, a permanent thyroid deficiency that is present from birth. "A new heterozygous FOXE1 variant segregated with 14-Alanine tract homozygosity in 5 CH siblings with athyreosis." (PMID 37008944, 2023). "The homozygous Ala-14 and the heterozygous p.Leu107Val FOXE1 variants were present in all the five siblings with athyreosis." (PMID 37008944, 2023). "This study started after the observation that the heterozygous FOXE1 variant p.Leu107Val segregated with severe CH and athyreosis in 5 siblings of our family." (PMID 37008944, 2023). "At last, among the few patients with FOXE1 heterozygous mutations that we previously identified only the Ala-14/14 genotype was associated with athyreosis." (PMID 37008944, 2023). "Nevertheless, in the few CH patients that have heterozygous FOXE1 variants, athyreosis was present only in the patient with Ala-14/14 genotype, while the Ala-14/16 and 16/16 genotypes were associated with GIS and hypoplasia." (PMID 37008944, 2023). "Interestingly, because athyreosis is not present, human thyroid formation and development do not depend entirely on FOXE1 activity." (PMID 28928994, 2017).
colon cancer (2 papers, 2020 to 2024). "The effects of FOXE1 on the growth of colon cancer cells and the expression of glycolytic enzymes were investigated in vitro and in vivo." (PMID 31918722, 2020). "To assess the role of FOXE1 in the proliferation of colon cancer cells, we overexpressed FOXE1 in HCT116 and LoVo cells." (PMID 31918722, 2020).
follicular adenoma (2 papers, 2019 to 2024). "High FOXE1 expression was detected in follicular adenomas compared to FTC, as well as in Graves’ disease samples compared to PTC cases." (PMID 39588344, 2024). "Japanese researchers studied five cancer related SNPs [rs966513 (9q22.33, FOXE1), rs944289 (14q13.3, PTCSC3), rs2439302 (8p12, NRG1), rs1867277 (9q22.23, FOXE1), and rs6983267 (8q24, POU5F1B)] in a cohort of 959 cases with follicular adenoma (FA), 535 cases with PTC, and 2766 controls." (PMID 31247975, 2019).
goiter (2 papers, 2014 to 2017). Enlargement of the thyroid gland usually caused by lack of iodine in the diet, hyperthyroidism, or thyroid nodules. "Earlier mutational screening excluded thyroid synthesis-related genes, the TSHR and FOXE1, to be the cause of CH and goiter in these two patients." (PMID 24745015, 2014).
lung carcinoma (2 papers, 2022 to 2024). "FOXM1 is overregulated in nine lung cancer datasets and is related to: 1) the negative regulation of transcription along with E2F1, FOXE1, and HMGA1; 2) cellular senescence along with E2F1, E2F3, and MYBL2; and 3) DNA repair and damage." (PMID 39228892, 2024).
renal carcinoma (2 papers, 2020 to 2024). A carcinoma arising from the epithelium of the renal parenchyma or the renal pelvis.
squamous cell carcinoma (2 papers, 2017 to 2024). A carcinoma arising from squamous epithelial cells. "Similarly, in squamous cell carcinoma, the 9q22 region of the chromosome (where FOXE1 is localized) is lost and, in other cancers, hypermethylation of promoter is also observed." (PMID 28928994, 2017).
chronic myelogenous leukemia (1 paper, 2024). "Pathways of interest included the BRACA1 PCC network, FoxE1 target genes, chronic myelogenous leukemia up, and GOMF RNA binding domains, among others, which were significantly enriched (up/down) in all models (Figure A3c)." (PMID 39057719, 2024).
colitis (1 paper, 2016). Inflammation of the colon. "Moreover, it has recently been suggested that detecting methylation of FOXE1 and SYNE1 genes in colitis-associated colorectal neoplasia could be a promising biomarker." (PMID 27517910, 2016).
colorectal adenoma (1 paper, 2024). An adenoma that arises from the colon or rectum. "Further studies are needed to investigate the role of FOXE1 in the evolution of colorectal adenoma to adenocarcinoma in the future." (PMID 38734646, 2024). "Our immunohistochemical results showed that the positive rate of FOXE1 protein in villous colorectal adenomas of the large intestine was significantly lower than that in tubular colorectal adenomas and serrated colorectal adenomas." (PMID 38734646, 2024). "The difference in FOXE1 protein expression in different types of colorectal adenomas may be related to tumor heterogeneity." (PMID 38734646, 2024). "We investigated FOXE1 expression in a total of 128 primary CRC tissues, 27 metastatic lymph node tissues, 29 colorectal adenomas (tubular adenoma, serrated adenoma, and villous adenoma) tissues, and 10 normal colorectal mucosal tissues by immunohistochemistry." (PMID 38734646, 2024).
colorectal tumor (1 paper, 2024). "We also analyzed FOXE1 methylation status in 10 normal colorectal tissues, 35 primary colorectal tumors, and paired adjacent non-tumor tissues." (PMID 38734646, 2024).
COVID-19 (1 paper, 2023). A disease caused by infection with severe acute respiratory syndrome coronavirus 2. "Endocrine-specific genes (e.g., HSD3B2, INS, IAPP, TSHR, FOXE1, LEP, and CRYGD) were deregulated in COVID-19 cases in an organ-specific manner." (PMID 37246981, 2023).
craniofacial clefts (1 paper, 2022). "Some of these proteins like Homeobox Protein BarH-like 1 (BARX1), Distal-Less Homeobox 4 (DLX4), Forkhead Box E1 (FOXE1), Homeobox Protein Hox-B3 (HOXB3), and Muscle Segment Homeobox 2 (MSX2) have been associated with the formation of craniofacial clefts." (PMID 37733420, 2022).
Gorlin syndrome (1 paper, 2017). "Therefore, the downregulation of FOXE1 may be related to the craniofacial abnormalities, such as mild microcephaly, observed in some Gorlin syndrome patients." (PMID 29088246, 2017).
hyperthyroidism (1 paper, 2018). Overactivity of the thyroid gland resulting in overproduction of thyroid hormone and increased metabolic rate. "The identified variants are therefore expected to be a mix of variants, which have been previously associated with hypo or hyperthyroidism (e.g., TPO, FOXE1, and ATXN2) and variants that lead to a TSH level, which is slightly above or below the population-based reference ranges." (PMID 30367059, 2018).
inflammatory bowel disease (1 paper, 2024). A spectrum of small and large bowel inflammatory diseases of unknown etiology. "Low expression of FOXE1 has been shown to be positively associated with inflammatory bowel disease (IBD).This suggests its potential value as a tumor marker in clinical diagnosis." (PMID 38734646, 2024).
lung squamous cell carcinomas (1 paper, 2020). "We observed that FOXE1 levels were elevated in several cancer types, with the most striking changes seen in esophagus and lung squamous cell carcinomas." (PMID 31846430, 2020).
lymph node metastasis (1 paper, 2024). "Meanwhile, low FOXE1 expression was significantly correlated with lymph node metastasis and advanced TNM stages, indicating its potential as a tumor marker." (PMID 38734646, 2024).
malignant struma ovarii (1 paper, 2024). An ovarian mature teratoma characterized by the presence of aberrant thyroid tissue with morphologic changes identical to thyroid carcinoma. "Here, we aimed to clarify the role of FOXE1 in Portuguese families (F1 and F2) with members diagnosed with malignant struma ovarii (MSO), an ovarian teratoma with ectopic malignant thyroid tissue, papillary TC (PTC) and CP." (PMID 38396644, 2024).
non-small cell lung carcinoma (1 paper, 2025). A group of at least three distinct histological types of lung cancer, including non-small cell squamous cell carcinoma, adenocarcinoma, and large cell carcinoma. "FOXE1 is overexpressed in non-small cell lung cancer (NSCLC), playing a role in the downregulation of autophagy markers and the upregulation of matrix metalloproteinases pathways." (PMID 41440381, 2025).
premature ovarian failure (1 paper, 2011). "FOXE1 is one of the candidate genes for genetic predisposition to premature ovarian failure (POF) and it contains an alanine tract." (PMID 22177572, 2011).
psoriasis (1 paper, 2022). An autoimmune condition characterized by red, well-delineated plaques with silvery scales that are usually on the extensor surfaces and scalp. "We found that psoriasis and AD share many DEGs and pathways, but also identified regulators, such as FOXE1, FOXM1, STAT3 and SOX7, and discovered a gene regulatory network unique for psoriasis." (PMID 35874668, 2022). "Of these nine regulators, four regulators (STAT3, FOXE1,PITX1,TFD) did not overlap with the top 30 regulators of AD, we consider these four regulators as key regulators for psoriasis." (PMID 35874668, 2022).
rosacea (1 paper, 2021). A chronic erythematous skin disorder that affects the face. "Among the 264 upregulated genes were 12 overlapped TFs in rosacea lesions, including STAT1, FOXE1 and ERG." (PMID 34290700, 2021).
thyroid hypoplasia (1 paper, 2014). Thyroid hypoplasia is a form of thyroid dysgenesis characterized by incomplete development of the thyroid gland that results in primary congenital hypothyroidism, a permanent thyroid deficiency that is present from birth. "We screened a hypothyroid child with thyroid hypoplasia for mutations in PAX8, TSHR, NKX2.1, NKX2.5 and FOXE1 genes." (PMID 25146893, 2014).
tubular adenoma (1 paper, 2024). A usually polypoid neoplasm arising from the glandular epithelium. "Interestingly, the high expression rate of FOXE1 in tubular adenoma and serrated adenoma was like that measured in normal colon mucosal tissues, while the FOXE1 expression level in villous adenoma was significantly decreased, being closer to the level in primary CRC." (PMID 38734646, 2024). "Interestingly, the high expression rate of FOXE1 in tubular adenoma and serrated adenoma was like that found in the normal colon mucosa, while FOXE1 expression in villous adenoma was significantly decreased, close to the level of that associated with primary CRC." (PMID 38734646, 2024).
xeroderma pigmentosum (1 paper, 2012). Xeroderma pigmentosum (XP) is a rare genodermatosis characterized by extreme sensitivity to ultraviolet (UV)-induced changes in the skin and eyes, and multiple skin cancers. "The association is likely attributed to FOXE1 rather than XPA which is involved in DNA excision repair and the skin disease xeroderma pigmentosum." (PMID 23251661, 2012).
tumor (35 papers, 2010 to 2025). "In the TPC-1 tumour cell model, both variants led to a decrease in FOXE1 promoter activity, compared with the WT (p < 0.005)." (PMID 38396644, 2024). "On the other hand, the c.-522G>T variant appears to have different impacts on FOXE1 promoter activity depending on the thyroid cell (normal versus tumour) context." (PMID 38396644, 2024). "SYNE1 and FOXE1 are two genes that have been recently linked to tumor growth, especially in gastrointestinal cancer." (PMID 33946400, 2021). "Histological analyses show that reduction of FOXE1 dosage results in the loss of the expected solid pattern of tumor growth, with the presence of empty structures resembling follicle remnants, partially filled with cells expressing thyroid markers." (PMID 33375029, 2020). "Correlation analysis showed that low expression of FOXE1 was significantly associated with poor clinicopathological features including advanced tumor stage and venous invasion." (PMID 31918722, 2020). "Thus, c.9C>T seems to be a loss-of-function variant, leading to lower FOXE1 promoter transcriptional activity in both normal and tumour cells." (PMID 38396644, 2024). "Hence, clarified of FOXE1 risk variants and their functions can be fundamental in tumor transformation." (PMID 32986379, 2020). "We observed reduced FOXE1 mRNA expression in tumors when compared to non-tumor samples, in accordance with FOXE1 expression in the TCGA dataset." (PMID 39588344, 2024). "Overall, the average mRNA expression levels of FOXE1 were significantly lower in tumour tissue compared with adjacent benign thyroid tissue, regardless of the FOXE1 mutation status." (PMID 38396644, 2024). "The hyperplastic tissues from the patients with FND revealed an intermediate degree of FOXE1 expression, between those of normal and tumour tissues, consistent with a decrease in the FOXE1 expression levels throughout the tumourigenic process." (PMID 38396644, 2024). "Through cell viability assay, monolayer, and soft agar colony formation assays, we found that the growth rate and proliferation ability of tumor cell lines were significantly decreased after being transfected with FOXE1." (PMID 38734646, 2024). "FOXE1 is a transcription factor with poorly defined function in senescence, whereas SPP1 encodes osteopontin, a secreted stromal protein involved in tumor growth." (PMID 35883188, 2022). "Tumours developed in BRAF FOXE1+/- background showed significantly reduced expression of all the genes investigated compared with those developed in BRAF FOXE1+/+ mice." (PMID 34299284, 2021). "Of note, the levels of FOXE1 in thyroid metastases (n = 8) were similar to those of the primary tumor samples and normal tissue, suggesting a role for FOXE1 in tumor progression." (PMID 31846430, 2020). "Of note, transgenic mice overexpressing FOXE1 in their thyroids displayed retardation in the proliferation of follicular cells, suggestive of its tumor suppressor function." (PMID 33551988, 2020). "In vivo study demonstrated that SW480 with silenced FOXE1 exhibited accelerated subcutaneous tumor growth." (PMID 31918722, 2020). "We show that genetically reduced Foxe1 levels impact on tumor histology, proliferation, and differentiation." (PMID 33375029, 2020). "For example, the FOXE1 TF is a critical tumor inhibitor that regulates tumor growth and glycolysis by suppressing HK2 in CRC." (PMID 32508884, 2020). "FOXE1 functions as a critical tumor suppressor in regulating tumor growth and glycolysis via suppressing HK2 in CRC." (PMID 31918722, 2020). "FOXE1 is a kind of thyroid transcription factors that play tumor suppressor role in the control of cell proliferation and tumor invasion in thyroid cells." (PMID 32986379, 2020).